DAB1 (DAB adaptor protein 1)
Description:
Signaling adapter of the reelin-mediated signaling pathway, which regulates the migration and differentiation of postmitotic neurons during brain development. Mediates intracellular transduction of Reelin signaling following reelin (RELN)-binding to its receptor: acts by docking proteins through its phosphotyrosine residues and PID domain.
Synonyms: SCA37
Tractability: PROTAC: UniProt records ubiquitination sites on it; ubiquitination databases record sites on it; its protein half-life has been measured.
Gene: Protein-coding gene on chromosome 1 (56,994,778 to 58,546,734, reverse strand). Ensembl gene ENSG00000173406.
Subcellular location: Cytoplasm
Subcellular location (Human Protein Atlas): Vesicles
Pathways (Reactome):
Developmental Biology: Reelin signalling pathway
Gene Ontology:
Molecular function: protein binding; signaling adaptor activity
Biological process: layer formation in cerebral cortex; neuron migration; reelin-mediated signaling pathway; lateral motor column neuron migration; regulation of synapse maturation; ventral spinal cord development
Cellular component: cytoplasm; cytosol; glutamatergic synapse; perinuclear region of cytoplasm; synapse
Genetic constraint (gnomAD): Loss-of-function variants: 12 observed, 47.75 expected, observed/expected ratio (o/e) 0.25, 90% interval 0.16 to 0.41. The upper end of that interval is the gene's LOEUF score, 0.41, which puts it in group 1 of 6, group 1 being the genes least tolerant of losing a copy. Missense variants: 495 observed, 608.86 expected, observed/expected ratio (o/e) 0.81, 90% interval 0.75 to 0.88. Synonymous variants: 200 observed, 222.06 expected, observed/expected ratio (o/e) 0.9, 90% interval 0.8 to 1.01.
Homologues: Orthologues: chimpanzee DAB1 (100% identical), macaque DAB1 (99% identical), dog DAB1 (99% identical), guinea pig DAB1 (97% identical), rat Dab1 (97% identical), mouse Dab1 (97% identical), rabbit DAB1 (94% identical), pig DAB1 (92% identical), tropical clawed frog dab1 (82% identical), zebrafish dab1a (72% identical), zebrafish dab1b (48% identical), Caenorhabditis elegans dab-1 (22% identical), and 9 more. Paralogues in human: DAB2 (38% identical), NUMB (19% identical), NUMBL (18% identical), NOS1AP (12% identical), LDLRAP1 (11% identical), FAM43A (9% identical), MAPK8IP1 (8% identical), FAM43B (8% identical), MAPK8IP2 (6% identical), GULP1 (5% identical), C1orf226 (3% identical).
Diseases named in the same sentence as DAB1 in open-access papers:
DAB1 is named in the same sentence as 92 diseases in open-access papers, as found by Europe PMC text mining. Sharing a sentence is not in itself a finding about the gene and the disease. The quoted sentences say what the papers report.
spinocerebellar ataxia type 37 (12 papers, 2019 to 2026). Spinocerebellar ataxia type 37 (SCA37) is a subtype of autosomal dominant cerebellar ataxia type 1 (ADCA type 1), characterized by a cerebellar syndrome along with altered vertical eye movements. "Remarkably, TTTTA/TTTCA expansions in intron 3 of DAB1 have initially been associated with spinocerebellar ataxia 37 (SCA37)." (PMID 38835431, 2021). "Spinocerebellar ataxia type 37 (SCA37) is caused by the pentanucleotide repeated insertion ATTTC between ATTTT/AAAAT repeats in the non-coding region of the reelin adaptor protein DAB1, which is necessary for brain patterning and synaptogenesis." (PMID 33671313, 2021). "Mutations in the NOTCH3 gene may promote the clinical presentation of spinocerebellar ataxia type 37 caused by mutations in the DAB1 gene." (PMID 34222332, 2021). "Reelin signaling dysregulation was also observed in the cerebellum of patients with SCA37 (spinocerebellar ataxia type 37) and was attributed to a mutation in the Dab1 chromosomal region." (PMID 37891846, 2023). "DAB1 gene [also known as spinocerebellar ataxia type 37 (SCA37)] located on 1p32.2 consists of 21 exons and encodes the adaptor protein reelin." (PMID 34707478, 2021). "DAB1 is involved in neuronal migration and is a responsible gene for spinocerebellar ataxia type 37." (PMID 39000095, 2024). "Here, we provide evidence that neurodevelopmental axonal defects initiate a motor phenotype in a zebrafish model of spinocerebellar ataxia type 37 (SCA37), a degenerative hereditary disease caused by an ATTTC repeat in the DAB1 gene." (PMID 41854242, 2026). "Also, for the three unrelated individuals with rare intronic TREs in DAB1, encoding a reelin adaptor protein, we confirmed the sizes of expanded ATTTT repeats, which are comparable to rare TREs reported by others at this locus for spinocerebellar ataxia type 37." (PMID 35546631, 2022).
cognitive deficits (8 papers, 2020 to 2025). "In addition, single nucleotide polymorphisms (SNPs) in the APOER2, VLDLR, and DAB1 genes are associated with cognitive impairments in patients with schizophrenia." (PMID 32982694, 2020). "These Dab1-positive complexes increased across the spectrum of sAD and correlated with pPSD95Thr19, Braak stage, Aβ plaque load, and cognitive deficits." (PMID 38093390, 2023). "These Dab1-positive complexes increased across the spectrum of sAD and correlated with pPSD95Thr19, NFT stage, Aβ plaque load, and cognitive deficits." (PMID 37333406, 2023). "We previously hypothesized a role of IgG against DAB1, AIFM1, and SURF1 in cognitive impairment in COVID-19, given the well-described functions of the three proteins in neurogenesis and synaptic plasticity." (PMID 40995367, 2025). "Single-target IHC revealed that five neuronal ApoER2 signaling partners (Dab1, pP85αTyr607, pLIMK1Thr508, pTauSer202/Thr205, pPSD95Thr19) accumulated in MCI and AD cases and positively correlated with histological progression and antemortem cognitive deficits." (PMID 40568659, 2025). "Interestingly, an adolescent high-fat diet has been shown to selectively reduce Reelin-positive cells without affecting the downstream DAB1 in the mPFC, resulting in deficient NMDA-dependent LTD and pronounced cognitive deficits." (PMID 36979424, 2023).
colorectal cancer (7 papers, 2019 to 2024). A primary or metastatic malignant neoplasm that affects the colon or rectum. "Prior studies have implicated DAB1 in the progression of various cancers, such as prostate cancer, colorectal cancer, and breast cancer." (PMID 38255219, 2024). "Along this line, Dab1 seems to play a role in tumor growth and metastatic progression and is part of a Notch-Dab1-ABL axis which promotes colorectal cancer invasion and metastasis." (PMID 33572344, 2021). "One of the genes induced by Notch signalling in colorectal cancer is Dab1 driving cancer cell proliferation and invasion by activation of a Dab1-Abl-RhoGEF protein Trio pathway." (PMID 33572344, 2021). "As formerly reported, DAB1 could be transcriptionally promoted in colorectal cancer via RBPJ, an important transcriptional factor of NOTCH pathway." (PMID 32415085, 2020). "Currently, there is a lack of research on the relationship between DNA methylation levels of the DAB1, FAM19A5, and PPP2R5C genes and colorectal cancer." (PMID 39199384, 2024). "In this study, we have identified three DMRs located within the DAB1 promoter region, FAM19A5 promoter region, and PPP2R5C intronic region that exhibit higher methylation levels in cancer tissues compared with adjacent tissues in Chinese colorectal cancer patients." (PMID 39199384, 2024).
schizophrenia (7 papers, 2015 to 2023). A major psychotic disorder characterized by abnormalities in the perception or expression of reality. "In exon-targeted resequencing using next-generation sequencing technology, rare variants of the DAB1 gene (p.G382C and p.V129I) were detected in patients with schizophrenia." (PMID 35163751, 2022). "DAB1 has been repeatedly reported to be associated with neurodevelopmental disorders including schizophrenia (SCZ) and autism spectrum disorders (ASD) in genetic, animal, and postmortem studies." (PMID 33298905, 2020). "Additionally, PDE4B is implicated in schizophrenia, whereas DAB1 truncated in our patient is required for synaptic function as well as associative learning in mice, and has been shown to be associated with autism." (PMID 26997977, 2016). "Several works linked schizophrenia to an imbalance of reelin, Gad67, and Dab-1 expression." (PMID 26526966, 2015). "Consistent with this possibility, behavioral abnormalities observed in schizophrenia, such as hyperactivity, decreased anxiety-like behavior, and impaired working memory, have been observed in dorsal forebrain-specific Dab1 conditional knock-out mice." (PMID 36941061, 2023). "Hiroki Kimura of Nagoya University Graduate School of Medicine and colleagues in Japan screened the protein-coding parts of the gene DAB1 in people with schizophrenia or autism for rare nucleotide variations." (PMID 33298905, 2020). "Furthermore, these mutants of the Dab1 protein were more unstable than the wild-type protein, which may diminish Reeln-Dab1 signaling and contribute to the pathology of schizophrenia." (PMID 35163751, 2022).
Alzheimer disease (6 papers, 2012 to 2025). A progressive, neurodegenerative disease characterized by loss of function and death of nerve cells in several areas of the brain leading to loss of cognitive function such as memory and language. "Prion infection further disrupted the Reelin signaling pathway, thus downregulating Dab1 and Reelin receptors and altering Reelin processing, like Alzheimer’s disease pathology." (PMID 40733546, 2025).
autism (6 papers, 2012 to 2023). Persistent deficits in social interaction and communication and interaction as well as a markedly restricted repertoire of activity and interest as well as repetitive patterns of behavior. "Four SNPs in DAB1 were found to be associated to ASD and were suggested to represent a risk factor for autism." (PMID 35422848, 2022). "Moreover, Tg rats showed abnormalities in Vldlr and Dab1 mRNA expression, similar to those detected in post-mortem brain from patients with autism." (PMID 23110844, 2012). "Moreover, Tg rats show abnormal expression of Vldlr and Dab1 mRNA, as detected in post-mortem brain from patients with autism." (PMID 23110844, 2012). "The first SNP, rs706363, is on the autism candidate gene DAB1 on chromosome 1." (PMID 23281790, 2012). "However, the authors confirmed that the interaction between RELN and DAB1 (OMIM *603448), encoding an intracellular adaptor which is tyrosine-phosphorylated when Reelin binds to lipoprotein receptors, may contribute to autism pathogenesis." (PMID 35422848, 2022).
Anxiety (5 papers, 2016 to 2024). Intense feelings of nervousness, tension, or panic often arise in response to interpersonal stresses. "DAB1 receives a tyrosine phosphorylation signal from RELN8; as such, RELN-DAB1 signaling may be associated with anxiety." (PMID 30158644, 2018). "A recent study revealed that DAB1 conditional knockout mice showed hyperactivity, decreased anxiety-like behavior, and a deficit in spatial reference and working memory." (PMID 37029353, 2023).
breast carcinoma (4 papers, 2019 to 2024). "In the context of breast cancer, a notable decrease in DAB1 expression has been linked to the triple-negative breast cancer subtype, along with associations to poor differentiation and lymph node metastasis." (PMID 38255219, 2024). "Dab1 promoted cell apoptosis by regulating NF‐κB/Bcl‐2/caspase‐9 pathway, considered as a potential tumor suppressor gene of breast cancer." (PMID 37491836, 2023). "Our results showed that Dab1 was reduced in breast cancer, and its compromised expression correlated with triple negative breast cancer phenotype, poor differentiation, as well as lymph node metastasis." (PMID 30484953, 2019). "Functional analysis in breast cancer cell lines demonstrated that Dab1 promoted cell apoptosis, which, at least partially, depended on its regulation of NF‐κB/Bcl‐2/caspase‐9 pathway." (PMID 30484953, 2019). "In this study, we examined the expression of Dab1 in 38 breast cancer paraffin sections, as well as 60 paired frozen breast cancer and their adjacent tissues." (PMID 30484953, 2019). "Our study strongly suggests that Dab1 may be a potential tumour suppressor gene in breast cancer." (PMID 30484953, 2019). "However, the exact function of Dab1 in breast cancer is unknown." (PMID 30484953, 2019). "Here, we found Dab1 was down‐regulated in breast cancer and displayed a negative correlation with triple negative breast cancer phenotype, poor differentiation, lymph node metastasis and other prognosis parameters." (PMID 30484953, 2019).
Ataxia (3 papers, 2017 to 2022). Ataxia refers to impaired coordination of voluntary muscle movement. "Dab1 mutant mice exhibit ataxia, tremors, a reeling gait, and neurons aberrantly positioned in laminated brain structures, demonstrating that Dab1 phosphorylation is critical for initiation of intracellular signaling." (PMID 28676854, 2017). "In this family, two different pathogenic mutations were found, a heterozygous repeat expansion in C9ORF72 in four patients with ALS/FTD and a heterozygous repeat expansion in DAB1 in at least nine patients with SCA, leading to a diagnosis of DAB1‐related ataxia (ATX‐DAB1; SCA37)." (PMID 36148898, 2022).
autism spectrum disorder (3 papers, 2016 to 2022). A spectrum of developmental disorders that includes autism, and Asperger syndrome. "Genetic and epigenetic changes in components of the Reelin-signaling pathway (RELN, DAB1) are associated with autism spectrum disorder (ASD) risk." (PMID 27184477, 2016).
glioblastoma (3 papers, 2023 to 2024). The most malignant astrocytic tumor (WHO grade IV). "The proliferation of glioblastoma cells were reduced by RELN signaling depending on mutant DAB1 stimulation." (PMID 37491836, 2023). "Pan-cancer analyses using The Cancer Genome Atlas datasets revealed that the levels of SMARCD3 and DAB1 mRNA expression were not correlated (R = 0.17, P < 2.2 × 10–16), including no positive correlation in low-grade glioma and glioblastoma (R = −0.11, P = 0.0023)." (PMID 36849558, 2023).
Lissencephaly (3 papers, 2016 to 2022). A spectrum of malformations of cortical development caused by insufficient neuronal migration that subsumes the terms agyria, pachygyria and subcortical band heterotopia. "In addition, biallelic splice variants of Dab1 were identified in a patient with mild lissencephaly and cerebellar hypoplasia, and these variants were suggested to affect the highly conserved functional phosphotyrosine-binding domain of Dab1." (PMID 35163751, 2022).
pancreatic cancer (3 papers, 2011 to 2021). "Interestingly, the same DAB1 (but somatic) splice mutation was found in the pancreatic cancer tissue of one FPC patient in a previous study." (PMID 34357098, 2021). "It was reported that the human DAB1 gene is located within an unstable common fragile site (CFS) region, and its expression level was decreased in many human cancer samples, including epigenetic silencing in pancreatic cancer cell lines." (PMID 21294906, 2011).
prostate carcinoma (3 papers, 2016 to 2024). A carcinoma that arises from epithelial cells of the prostate gland. "The upregulation of DAB1 mediated the inhibition of migration and invasion of prostate cancer cells by regulating microRNA‐300." (PMID 37491836, 2023). "Interestingly, the accumulation of CRL substrates induced by SAG knockdown was rather selective, since other two SCF/CRL1 substrates p21 and p27, two CRL5 substrates FLNA and DAB1, and one CRL3 substrate NRF2 were not accumulated in these two lines of prostate cancer cells upon SAG depletion." (PMID 27955654, 2016).
bipolar disorder (2 papers, 2023 to 2025). A disorder of the brain that causes unusual shifts in mood, energy, activity levels and the ability to carry out day-to-day tasks. "Dysfunction of Reelin–Dab1 signaling can lead to behavioral deficits in individuals with SCZ and bipolar disorder." (PMID 40740482, 2025).
cardiomyopathies (2 papers, 2021 to 2022). "Moreover, interactions among DAB1 or NOTCH3 and respective proteins using the STRING database suggested the potential effects on the development of cardiomyopathies." (PMID 34222332, 2021).
chronic gastritis (2 papers, 2015 to 2024). Inflammation of the stomach that is chronic in nature. "Previous research has identified DAB1 mutations in Chinese patients with chronic gastritis and peritoneal metastasis of gastric cancer, and reduced DAB1 mRNA expression has been observed in various cancers." (PMID 39408230, 2024). "We noticed that 6 somatic variations (ATXN3, PLIN4, PDZD2, MUC4, DMBT1 and DAB1) were simultaneously observed in triple samples of chronic gastritis, primary cancer and PM cancer." (PMID 26330360, 2015).
chronic kidney disease (2 papers, 2017 to 2021). Impairment of the renal function secondary to chronic kidney damage persisting for three or more months. "Therefore, the Dab1-p38 signaling pathway might be a novel candidate therapeutic target in order to decrease podocyte apoptosis in chronic kidney diseases." (PMID 28676854, 2017).
COVID-19 (2 papers, 2022 to 2025). A disease caused by infection with severe acute respiratory syndrome coronavirus 2. "We previously identified IgG autoantibodies targeting epitopes within brainstem proteins—disabled homolog 1 (DAB1), apoptosis-inducing factor 1 (AIFM1), and surfeit locus protein 1 (SURF1)—as markers of severe acute COVID-19." (PMID 40995367, 2025). "Further, in our gene-based analysis, five genes (DAB1, ASIC2, MAGI1, CSMD1 and PTPRD) were shared between T2D and COVID-19." (PMID 36482905, 2022). "After comparing the significant genes in T2D and COVID-19, five genes were found to be shared between T2D and COVID-19: PTPRD, CSMD1, MAGI1, ASIC2, DAB1." (PMID 36482905, 2022).
depression (2 papers, 2024 to 2025). "Of 10 GWAS studies of MDD or depression, two found an association between DOCK2 and MDD/depression, and four indicated loci in UGT8, PTPRM, or DAB1 as variants associated with MDD/depression." (PMID 39287932, 2024).
Hypertension (2 papers, 2017 to 2021). The presence of chronic increased pressure in the systemic arterial system. "In the present study, our data revealed that Ang II-infused rats developed hypertension, proteinuria, and podocyte injury accompanied by Dab1 phosphorylation and increased reelin expression in kidney." (PMID 28676854, 2017). "Interestingly, a previous study has shown that DAB1 phosphorylation and increased reelin expression in the glomeruli are accompanied by hypertension, proteinuria, and podocyte injury in the Ang II-infused rats." (PMID 33924028, 2021).
Intellectual disability (2 papers, 2016 to 2020). "We also determined the transcript levels of six candidate genes (DAB1, HOOK1, NFIA, DOCK7, DNAJC6 and PDE4B) for syndromic intellectual disability." (PMID 26997977, 2016). "We propose six candidate genes (DAB1, HOOK1, DOCK7, DNAJC6, PDE4B, and NFIA) for the clinical features such as intellectual disability and OCD observed in DGDP005, because each of these genes is involved directly or indirectly in neurological disorders." (PMID 26997977, 2016). "Comparative deletion mapping showed that there are at least six candidate genes including, NFIA, HOOK1, DOCK7, DAB1, DNAJC6, and PDE4B, that could contribute to the syndromic or non-syndromic intellectual disability." (PMID 26997977, 2016).